RNU6-1255P (RNA, U6 small nuclear 1255, pseudogene)
Gene: Small nuclear RNA gene on chromosome 8 (130,069,541 to 130,069,652, reverse strand). Ensembl gene ENSG00000200304.
Homologues: Orthologues: chimpanzee U6 (96% identical), macaque U6 (88% identical), dog U6 (69% identical), guinea pig U6 (64% identical), mouse Gm22597 (58% identical), rat LOC120093920 (54% identical). Paralogues in human: RNU6-15P (74% identical), RNU6-1 (73% identical), RNU6-11P (73% identical), RNU6-14P (73% identical), RNU6-2 (73% identical), RNU6-37P (73% identical), RNU6-3P (73% identical), RNU6-4P (73% identical), RNU6-5P (73% identical), RNU6-6P (73% identical), RNU6-7 (73% identical), RNU6-8 (73% identical), and 1285 more.